CRP (C-reactive protein)
Diseases named in the same sentence as CRP in open-access papers (continued):
Sharing a sentence is not in itself a finding about the gene and the disease.
atherosclerosis (continued). "The present Mendelian randomization study found that there was a causal association between CRP and atherosclerosis, and the relationship between the two was positive, i.e., CRP could increase the risk of atherosclerosis in large arteries." (PMID 40779499, 2025). "At the molecular level, the formation of NLRP3 inflammatory vesicles in macrophages is a key step in the spread of inflammation, and the NLRP3/IL-1/IL-6/hypersensitive CRP (hs-CRP) classical inflammatory pathway is closely associated with the increased risk of atherosclerosis." (PMID 40182041, 2025). "Among inflammatory mediators associated with atherosclerosis, CRP might be a potent predictor for CVD in patients with SLE." (PMID 40725777, 2025). "C-reactive protein (CRP) plays an important role in the development of atherosclerosis, being implicated in release of proinflammatory cytokines, promotion of endothelial dysfunction, induction of tissue factor expression, activation of complement pathway and inhibition of nitric oxide synthesis." (PMID 39240753, 2025). "Consequently, inflammatory markers such as high-sensitivity CRP (hs-CRP), tumour necrosis factor, and interleukins (ILs) have been shown to be associated with increased risk of atherosclerosis and cardiovascular events." (PMID 40278206, 2025). "Similarly, increased levels of CRP and pro‐inflammatory cytokines have been found to be associated with the development of premature atherosclerosis in patients with SLE." (PMID 39743740, 2025). "Therefore, it is crucial to investigate how TCZ affects atherosclerosis because IL-6 and CRP are linked to CVD, even in healthy males." (PMID 39897309, 2025). "High CRP levels may indicate heightened arterial inflammation, contributing to atherosclerosis progression and an elevated risk of ischemic events." (PMID 38983990, 2024). "Harmful components in SHS, such as nicotine and carbon monoxide, impair vasodilatory function and increase the risk of atherosclerosis; simultaneously, oxidative stress and elevated markers of inflammation (e.g. C-reactive protein) induced by SHS further promote vascular pathology and thrombosis." (PMID 38966818, 2024). "Systemic inflammation, a hallmark of atherosclerosis, likely plays a crucial role, with elevated inflammatory markers such as interleukin-6, tumor necrosis factor-α, and highly sensitive c-reactive protein contributing to oxidative stress and endothelial dysfunction." (PMID 39272707, 2024). "Paricalcitol supplementation may therefore reduce the risk of atherosclerosis in CKD patients by decreasing CRP levels." (PMID 38395972, 2024). "Beyond serving as a marker for atherosclerosis, elevated CRP levels may contribute to an increased risk of PAD." (PMID 39429407, 2024). "Additionally, inflammation mediated by hyperglycemia and IR was considered a significant risk factor in the development of atherosclerosis, with C-reactive protein (CRP) often serving as a predictor of cardiovascular events." (PMID 39737158, 2024). "Interestingly, the CEC was associated with the rapid progression of atherosclerosis in those with a high CRP concentration at the initial assessment, users of prednisone, and non-users of methotrexate or biological DMARDs." (PMID 39456762, 2024). "As atherosclerosis is associated with inflammation within the vessel walls, CRP may also be an indicator of cardiovascular risk." (PMID 38673472, 2024). "According to one study, the development of atherosclerosis may raise CRP levels, which in turn causes problems with lipid metabolism, platelet aggregation, and ultimately thrombosis." (PMID 37634408, 2023). "In this context, several inflammatory markers, such as high-sensitivity C-reactive protein (hs-CRP) and fibrinogen blood levels, as well as the number of leukocytes, are recognized as predictable risk factors of atherosclerosis and other cardiovascular diseases." (PMID 36983201, 2023).
atherosclerosis (continued). "Finally, we have not evaluated some new promising biomarkers of cardiovascular risk prediction and atherosclerosis, such as high-sensitivity C-reactive protein, fibrinogen, matrix metalloproteinases, and myeloperoxidase." (PMID 36939826, 2023). "A recent study showed that in a population of patients at high risk for or with atherosclerosis, hs-CRP was a stronger predictor of cardiovascular events, cardiovascular death, and all-cause death than residual cholesterol risk (as measured by low-density lipoprotein cholesterol)." (PMID 37765050, 2023). "The relevance of carotid intima-media thickness as a surrogate marker for generalized atherosclerosis is well-established, and its association with inflammatory markers like C-reactive protein and oxidized LDL highlights its potential in cardiovascular disease research." (PMID 38201926, 2023). "However, the underlying mechanism involving CRP inthe development of atherosclerosis via its influence on endothelial functionrequires further investigation, with a special focus on the two distinctisoforms." (PMID 39077585, 2023). "In the present study, the authors showed significantly increased CRP levels in the patient group which may show us a higher prevalence of underlying atherosclerosis and cardiovascular disorders in psoriasis patients." (PMID 37198010, 2023). "Furthermore, CEC is a reliable marker of HDL function and improves atherosclerosis risk prediction beyond coronary artery calcium score, family history of coronary artery disease, and high sensitivity C-reactive protein." (PMID 36891247, 2023). "Most of the previous evidence points to the hypothesis that CRP is rather a marker of progressing atherosclerosis than a causal risk factor for CVD." (PMID 37623831, 2023). "However, the causal estimate for atherosclerosis-CRP was based only on a single SNP analysis (rs1980496)." (PMID 37298077, 2023). "CRP, a sensitive indicator of inflammation, is closely associated with the progression and instability of atherosclerotic plaques which are a major contributor to the recurrence of vascular events in patients with atherosclerosis in large arteries." (PMID 37679730, 2023). "The aftermath activation of CRP may inhibit endothelium-dependent vasodilation and nitric oxide synthesis, suggestive to cause arterial stiffness and trigger atherosclerosis." (PMID 36971865, 2023). "We hypothesized that clinical periodontal indices, the cytokine profile in GCF and serum of PD patients, and serum inflammatory parameters (CRP and fibrinogen) are independent risk factors for subclinical atherosclerosis compared with lipid profiles." (PMID 36983201, 2023). "Indeed, research has shown that higher levels of both CRP and IL-1β are associated with atherosclerosis in the brain, reduced white matter fractional anisotropy (i.e., microstructural integrity), and impaired synaptic plasticity and neurogenesis." (PMID 36612568, 2022). "Additionally, it was observed that DANCR was significantly associated with LDL-C, Hcy, and CRP levels, which are well-known risk factors for atherosclerosis and related cardiovascular diseases." (PMID 35235755, 2022). "It is important to note that per se CRP is a potent modulator of pro- and anti-inflammatory cytokines, as well as other chemokines and adhesion molecules that are also implicated in the process of atherosclerosis." (PMID 36358491, 2022). "CRP is a proinflammatory molecule involved in diverse reactions that are related to the activation of the inflammatory process associated with the development of atherosclerosis and other cardiovascular events." (PMID 35268023, 2022). "Interestingly, CRP has been also associated with the immunologic process that gives rise to vascular remodeling and plaque deposition which are crucial for atherosclerosis development and thrombus formation." (PMID 35625480, 2022).
atherosclerosis (continued). "As high plasma cholesterol levels are related to the development of CVD, we determined how different kefir preparations impacted circulating levels of VCAM-1 and CRP, which are important factors in the development of atherosclerosis and common biomarkers of CVD risk." (PMID 36504827, 2022). "Long-term exposure to ambient PM2.5 may increase blood C-reactive protein and oxidative stress, causing systemic inflammation, which in turn may lead to atherosclerosis and adversely alter vascular functions." (PMID 36506713, 2022). "CRP levels, which are considered a sensitive marker of systemic inflammation, were linked to the higher rates of PE and immunologic processes associated with atherosclerosis development and thrombus formation." (PMID 35625480, 2022). "COPD causes an increase in inflammatory markers and mediators, including TNF-α, IL-6, and C-reactive protein (CRP), to name a few, and can cause other forms of complications, including lung cancer, stroke, cardiovascular diseases, atherosclerosis, and myocardial ischemia." (PMID 36145202, 2022). "In addition, high-sensitivity CRP (hs-CRP), a sensitive and more precise biomarker of inflammation, provides results associated with a higher risk of atherosclerosis and all-cause and CVD mortalities." (PMID 33806677, 2021). "In addition, enhanced CRP levels are also regarded as a significant risk element for atherosclerosis, stroke, and myocardial infarction." (PMID 34720749, 2021). "In addition, inflammation-related markers, such as hsCRP, have also been demonstrated as key risk factors for atherosclerosis, and CRP is deposited in the arterial wall during atherogenesis." (PMID 34876165, 2021). "However, a large number of studies have revealed that CRP plays a direct pathogenic role in vascular injury and acts as an important pro-inflammatory factor in the process of atherosclerosis." (PMID 34571772, 2021). "Furthermore, the relationships of PWV and ABI with skin AFseemed to be stronger than with several other classic risk factors for atherosclerosis such as CRP, HbA1c, and even age." (PMID 34176469, 2021). "Tooth loss is the ultimate stage of periodontal disease and may be associated with an increase in C‐reactive protein (CRP), which itself is implicated in atherosclerosis and thus in the occurrence of stroke." (PMID 33797859, 2021). "Moreover, in one retrospective study, patients with a history of stroke after prescribing pitavastatin showed a reduced CRP level and potentially limited atherosclerosis in high-risk stroke patients." (PMID 34489618, 2021). "On the other hand, the change of C-reactive protein (CRP) among motorbikes drivers and controls groups reveals a systemic inflammatory response including stimulation of the bone marrow and progression of atherosclerosis with the risk of development of cardiovascular diseases." (PMID 33466768, 2021). "Whether increased levels of CRP only reflect the underlying inflammatory state associated with atherosclerosis and heart disease or is directly involved in the pathogenesis of cardiovascular disease, is not clear." (PMID 34649504, 2021). "In line with previous studies assessing the relevance of a multimarker approach for atherosclerotic risk assessment, our data indicate that high SDF-1 alone or even better when combined with high CRP levels were strongly associated with prevalent clinical atherosclerosis manifestations." (PMID 34062730, 2021). "Indeed, both osteoporosis and atherosclerosis have been linked to an overall inflammatory state and the levels of CRP, IL-6, and TNF-α directly correlated to the bone resorptive action of monocytes." (PMID 34610044, 2021). "Furthermore, HT, habitual smoking, age, C-reactive protein, and blood sugar are risk factors of atherosclerosis." (PMID 34243715, 2021).
atherosclerosis (continued). "In addition, ESR and CRP levels were significantly higher in the patient group, thereby supporting the idea that inflammation is a major risk factor for asymptomatic atherosclerosis in RA patients." (PMID 33259776, 2021). "In addition, MMP-10 expression is induced by CRP in human endothelial cells and both parameters positively correlated with subclinical atherosclerosis in asymptomatic subjects with CV risk factors." (PMID 34062730, 2021). "Interestingly, TNF-alpha and CX3CR1 expression positively correlated with increased intima-media thickness and hs-CRP, both of which are markers of atherosclerosis and cardiovascular risk." (PMID 34439835, 2021). "The increase CRP expression might be one of the underlying mechanisms behind atherosclerosis in hyperleptinemia." (PMID 34178553, 2021). "Although not established but it is thought that nicotine and carbon monoxide, elevated CRP (C-reactive protein) and fibrinogen levels may be also involved in atherosclerosis and associated inflammatory cascades." (PMID 34221284, 2021). "We hypothesized that this CRP mutant, unlike wild-type CRP, could be anti-atherosclerotic and, accordingly, the effects of mutant CRP on atherosclerosis in atherosclerosis-prone LDL receptor-deficient mice were evaluated." (PMID 32849641, 2020). "CRP is an early biomarker for inflammation and a good indicator of atherosclerosis risk." (PMID 33212852, 2020). "Thus, CRP is commonly used for the risk stratification of cardiovascular disease, as well as a marker of generalized atherosclerosis." (PMID 33008437, 2020). "CRP in atherosclerosis patients not only serves as a biomarker of cardiovascular disease risk but it also plays a part in mediating atherosclerosis by promoting arterial endothelial activation and mediating inflammatory reactions and the innate immune response." (PMID 32358950, 2020). "Moreover, ubiquitin was suggested to be positively related to inflammatory markers CRP, CK-MB and cTnl, which were associated with progression of atherosclerosis as well as AMI." (PMID 32990315, 2020). "C-reactive protein (CRP) is an acute inflammatory protein, produced predominantly in the liver, in response to several cytokines, which induce endothelial dysfunction, accelerate progression of atherosclerosis and increase the risk of cardiovascular disease." (PMID 32443557, 2020). "In summary, more research is needed to elucidate whether CRP causally contributes to atherosclerosis progression in humans." (PMID 33158028, 2020). "Similarly, persistent elevations in CRP, or low-grade inflammation, have been linked to higher risk of coronary heart disease and in the pathophysiology of atherosclerosis." (PMID 31992316, 2020). "So, it is possible that by using an ultrasensitive method, we might have found an association between CRP and subclinical atherosclerosis." (PMID 31517250, 2019). "In rabbits, CRP has been found associated with the progression of atherosclerosis." (PMID 31114584, 2019). "For instance, high CRP levels have been linked with the progression of atherosclerosis in uraemia and evidences suggest that CRP may play a direct role in atherogenesis." (PMID 31316299, 2019). "It has previously been claimed that statins are most effective in the presence of inflammation and that patients achieving the greatest CRP reductions due to statin therapy experience the largest risk reductions, which would be consistent with a causal role for inflammation in atherosclerosis." (PMID 29146277, 2018). "Since inflammatory nature of atherosclerosis have been demonstrated both in animal models as well as in clinical studies a link has been suggested between high sensitivity C-reactive protein (CRP) with coronary artery disease (CAD) risk." (PMID 29867478, 2018). "Fourth, Tooth loss is the ultimate stage of periodontal disease and may be associated with an increase in C-reactive protein (CRP), which itself is implicated in atherosclerosis and thus in the occurrence of stroke." (PMID 29590166, 2018).
atherosclerosis (continued). "Therefore, CRP is a sensitivity index for inflammation, and the development and progression of atherosclerosis are directly linked to the risk of atherosclerosis indicators." (PMID 30142970, 2018). "Lox-1 upregulation is observed in atherosclerosis and linked to oxidative stress and inflammatory reactions leading to inhibition of Nos3 enzymatic activity via increased C-reactive protein production and, consequently, microvessel dysfunction in the periphery." (PMID 30410436, 2018). "Consistent with this point of view, CRP has been implicated in the pathogenesis of atherosclerosis and appears to be not only a consistent predictor of cardiovascular events but an independent risk factor for myocardial infarction, stroke, and peripheral vascular disease as well." (PMID 29535705, 2018). "Since atherosclerosis may start in childhood, hs-CRP is associated with the risk of early onset of cardiovascular disease in children." (PMID 28946611, 2017). "CRP in concentrations below 10 mg/L (hsCRP) can be used for atherosclerosis risk assessment." (PMID 26771632, 2016). "Recently, a phase II clinical trial using a CCR2 neutralizing antibody MLN1202 found a decrease in C-reactive protein in patients with high risk of atherosclerosis, suggesting the potential for the suppression of inflammation, plaque angiogenesis and ultimately plaque progression." (PMID 27834814, 2016). "The CRP level may also be associated with atherosclerosis and its progression; in our study, it was marginally associated with the Rutherford grade." (PMID 27760183, 2016). "The associations between RBC n-3 DPA, CRP, and fasting TG may have important implications for the prevention of atherosclerosis and chronic inflammatory diseases and warrant further study." (PMID 26247967, 2015). "In view of epidemiologic evidence associating high CRP levels with cardiovascular risk—reflecting the biologic impact it bears on atherosclerosis—measurement of serum levels of high-sensitivity CRP has been proposed as a tool for assessment of cardiovascular risk." (PMID 27433484, 2014). "Formally, experimental approaches to investigate the role of CRP in mouse models necessitated the introduction of transgenes overexpressing human or rabbit CRP to murine strains or the generation of CRP-deficient mice that have been rendered prone to atherosclerosis." (PMID 24872599, 2014). "Cystatin C is associated with biochemical atherosclerosis markers such as CRP and homocysteine." (PMID 24478035, 2014). "Increased plasma levels of C-reactive protein (CRP) are closely associated with cardiovascular diseases, but whether CRP is directly involved in the pathogenesis of atherosclerosis is still under debate." (PMID 24872601, 2014). "Thus, we should not stop our investigations at the “marker versus maker” debate on CRP but try to understand the inflammatory process associated with atherosclerosis." (PMID 24808639, 2014). "CRP is known to be an important risk factor for native atherosclerosis and native CAD." (PMID 25490200, 2014). "This strong base of epidemiological evidence has led to the hypothesis that CRP is both a marker of and a causal mediator for the development of atherosclerosis." (PMID 24872599, 2014). "Because atherosclerosis is regarded as an inflammatory disease, statins were speculated to benefit high-risk cardiovascular patients by reducing systemic levels of CRP." (PMID 23950953, 2013). "Current hypotheses state that the increased CRP observed in dialysis patients reflects the severity of an “inflammatory state,” caused by dialysis itself, vessel inflammation due to atherosclerosis, and oxidative stress generated by uremia." (PMID 24007461, 2013). "In addition to being an acute-phase inflammatory marker, CRP is also considered the causative factor of low-grade vascular inflammation in atherosclerosis." (PMID 23950953, 2013).